CDH2 (cadherin 2)
Diseases named in the same sentence as CDH2 in open-access papers (continued):
Sharing a sentence is not in itself a finding about the gene and the disease.
cancer (continued). "Finally, we evaluated the expression of hub genes with the development of one of the main complications of IPF patients, LUAD and LUSC, and observed that six of them (CDH2, SPP1, TNC, CYR61, SERPINA1, and IL6) were correlated with the progression of different cancer stages." (PMID 37887075, 2023). "Moreover, we found a positive correlation between mRNAsi with CDH1 (epithelial marker) and a negative correlation between mRNAsi and CDH2 (mesenchymal marker), suggesting a negative relation between mRNAsi and cancer metastasis in iCCA." (PMID 36712866, 2022). "In addition, the M genes that exhibited dynamic compartment changes across the cancer cell lines were enriched in the biological process related to anatomical structure morphogenesis, including COL5A2, LOX, CDH2, ZEB1, and AXL (FDRdynamic = 1.22 × 10−8)." (PMID 35637517, 2022). "Furthermore, we found that the membrane proteins CDH2, EGFR, ITGA3, ITGA5, ITGB1, and CALR may have significant effect on cancer prognosis and outcomes, which were further validated in vitro." (PMID 33005184, 2020). "Therefore, correlations between CDH1, CDH2, and ZEB1 genes that have been described in cancer may also exist in early zebrafish development." (PMID 23667256, 2013). "While CDH2 and CEACAM6 are known to have elevated expression in various cancers, to the best of our knowledge no clear role or association between DCAF7 and cancer has so far been described." (PMID 41160880, 2026). "Although we did not observe obvious morphological changes in cancer cells after miR-182 overexpression, the EMT marker proteins, namely CDH1, CDH2 and Vimentin, were modestly regulated by miR-182." (PMID 27996004, 2016). "In addition, compared to liver metastatic cancer tissues, CP, HP, TF, and SERPINA5 were upregulated in normal liver tissues, while the expression CDH2 and SPARCL1 did not exhibit significant differences between the two tissues." (PMID 34422629, 2021).
infection (33 papers, 2010 to 2026). The state of being infected such as from the introduction of a foreign agent such as serum, vaccine, antigenic substance or organism. "At the same time, an apparent inhibition of Snail and Cdh2 expression was observed after synchronization, consistent with our observations of the infection efficiency test." (PMID 22529890, 2012). "In summary, plasma CDH2 level may be influenced by status HIV of infection." (PMID 28358908, 2017). "However, our screening also identified invasion- and migration-related genes that were not significantly modulated upon infection (i.e., PAPPA, SNAIL, MMP9, MMP11, ICAM1, CTNNB1, and CDH2)." (PMID 41450565, 2025).
adenocarcinoma (22 papers, 2003 to 2024). A common cancer characterized by the presence of malignant glandular cells. "Heatmap analysis revealed upregulated VIM and PLK1 mRNA expression in TGF-β-treated adenocarcinoma when the mesenchymal markers CDH2, SNAI1, and SNAI2 were high and either CDH1 or OCLN (epithelial markers) was low in majority of LUAD cells analysed." (PMID 33963314, 2021). "miR-9-5p activates N-cadherin by acting on Twist1 to promote EMT in cervical squamous cells, and promotes EMT in adenocarcinoma cells by inhibiting cadherin 1 (CDH1) and activating cadherin 2 (CDH2)." (PMID 35805066, 2022).
prostate (6 papers, 2020 to 2022). "Elevated levels of RBP4 and cadherin-2 signal early stages of prostate carcinogenesis, while ENO1, T-kininogen 2 and IDH2 represent more advanced stages." (PMID 35886909, 2022).
hematological malignancies (5 papers, 2020 to 2024). "Shown are colocalized CDH2 and Cx43 in cytokeratin+ cells (green + red + blue = white areas) as well as in some sections from hematological malignancies." (PMID 34078741, 2021). "Interestingly, there was colocalized Cx43/CDH2 (within very few cells) in BM biopsies of patients with hematological malignancy." (PMID 34078741, 2021). "However, the percentages of colocalized CDH2 and Cx43 in hematological malignancies were significantly (P < 0.05) less than the number of slides with positive colocalized CDH2/Cx43 from BC patients." (PMID 34078741, 2021).
neurological diseases (5 papers, 2017 to 2023). "Below, we summarize various neurological diseases linked to Cdh2 in the last 10 years and provide details of the underlying molecular mechanisms where it is available." (PMID 36213737, 2022). "In the past few years, direct and indirect evidence linked CDH2 to various neurological diseases, and in this review, we summarize recent developments regarding CDH2 function and its involvement in pathological alterations of the CNS." (PMID 36213737, 2022).
cardiac disease (4 papers, 2010 to 2024). "The role of the classical cadherin CDH2 or N-cadherin is well established in normal cardiac function as well as in the pathogenesis of a number of cardiac diseases and disorders." (PMID 35011717, 2022).
neurodevelopmental disorder (4 papers, 2021 to 2025). A behavioral and cognitive disorder with onset during the developmental period that involves impaired or aberrant development of intellectual, motor, or social functions. "Nonetheless, de novo pathogenic variants in Cdh2, targeting EC4 and EC5 domains, cause neurodevelopmental disorders with defects in callosal projections from mild hypoplasia to complete agenesis, suggesting the implication of Cdh2 in the control of this type of axonal projections." (PMID 33435191, 2021).
genetic diseases (1 paper, 2022). "Therefore, CDH2 appears to cause human genetic diseases, such as ARVC and ACOG syndrome." (PMID 36111109, 2022).
CDH2 also shares sentences with these, for which no sentence is quoted: nasopharyngeal carcinoma (16 papers); renal carcinoma (14); renal cell carcinoma (14); cholangiocarcinoma (13); liver fibrosis (10); ovarian tumor (10); metastatic melanoma (9); papillary thyroid cancer (9); oral squamous cell carcinoma (8); heart failure (7); invasive carcinoma (7); pancreatic ductal adenocarcinoma (7); renal fibrosis (7); adenoma (6); adenomyosis (6); atherosclerosis (6); bladder tumors (6); brain tumors (6); chondrosarcoma (6); chronic myeloid leukemia (6); pancreatic adenocarcinoma (6); brain cancer (5); colorectal tumor (5); cutaneous melanoma (5); head and neck squamous cell carcinoma (5); myocardial hypertrophy (5); pituitary tumor (5); urothelial bladder cancer (5); benign tumors (4); Embryonic Carcinoma (4).
A further 236 diseases each share a sentence with CDH2 in 4 papers or fewer.